COA6 (cytochrome c oxidase assembly factor 6)
Diseases named in the same sentence as COA6 in open-access papers (continued):
Sharing a sentence is not in itself a finding about the gene and the disease.
tumor (continued). "Hypomethylation generally correlates with increased transcriptional activity, supporting the hypothesis of an enhanced immune response in tumours with high COA6 expression." (PMID 40596639, 2025). "Furthermore, CellChat analysis of intercellular communication demonstrated that tumour epithelial cells with high COA6 expression formed a more robust signalling network, indicating enhanced cellular communication capacity." (PMID 40596639, 2025). "This reduction in chemokine expression implies that COA6 may suppress the recruitment of immune cells, further contributing to immune evasion by the tumour." (PMID 40596639, 2025). "These interactions were particularly enriched in regions of high COA6 expression, suggesting a spatially coordinated network of tumour‐immune‐stromal cross‐talk that may influence tumour progression, immune evasion and therapeutic response." (PMID 40596639, 2025). "Among these, COA6 stood out due to its significant differential expression between tumour and normal tissues in single‐cell RNA‐sequencing (scRNA‐seq) analysis, and a strong concordance between its GWAS and eQTL effect sizes, suggesting a robust genetic link to PDAC pathogenesis." (PMID 40596639, 2025). "Furthermore, when considering tumor stage that combines tumor size, lymph node metastasis, and distant metastasis, COA6 mRNA amounts were elevated in stage II cases compared with the stage I group (p<0.05)." (PMID 39132153, 2024). "However, based on T (tumor size) stage, COA6 mRNA amounts were significantly elevated in the T2 and T3 groups compared with T1 cases (p<0.05)." (PMID 39132153, 2024). "These may explain why the expression of COA6 was associated with tumor stage and T stage in LUAD and patients with a higher expression of COA6 were of shorter OS." (PMID 36982777, 2023). "Blockade of β-adrenergic receptor signalling reverts endothelialcell metabolism from aerobic glycolysis towards oxidative phosphorylationthrough cytochrome C oxidase assembly factor 6 (Coa6) activity, therebyinhibiting angiogenesis and curtailing tumour progression." (PMID 33465324, 2021). "Visualisation of COA6 expression across tissue sections revealed marked spatial heterogeneity: higher expression levels were observed in specific populations—particularly population 3 and population 7—which were predominantly located within the tumour core and perivascular regions." (PMID 40596639, 2025). "Additionally, the enrichment of genes regulating the G2/M phase transition within the cell cycle pathway indicates that COA6 may drive tumour growth by promoting accelerated cell division." (PMID 40596639, 2025). "Thus, we propose that COA6 is possibly involved in MYC-mediated tumor promotion." (PMID 36982777, 2023). "Therefore, we suggest that COA6 may promote the proliferation of LUAD cells by multiple tumor promotion pathways including MYC, PI3K–AKT–mTOR, and ROS." (PMID 36982777, 2023). "Specifically, the T cell_inflamed signature, which typically indicates active T‐cell infiltration and immune activation within the tumour microenvironment (TME), was notably reduced in the COA6‐high expression group." (PMID 40596639, 2025). "Mechanistically, it was found that high COA6 expression stimulates OXPHOS, providing an energy boost for tumor cell growth." (PMID 39132153, 2024). "Together, we propose that the uplifted COA6 level is closely related to the enhanced OXPHOS, which is beneficial to tumor growth and leads to the poor prognosis of LUAD patients." (PMID 36982777, 2023). "Compared with the results of the TCGA database, only the COA6 and ATP6AP1 expressions were significantly different between LIHC tumor tissues and normal tissues from the GEPIA2 database." (PMID 36313717, 2022). "ATP7A (P = 0.008), COA6 (P = 0.016), TMEM199 (P = 0.024) and FDX1 (P = 0.004) expression were significantly related to tumor stage (T classification)." (PMID 36313717, 2022).
tumor (continued). "COA6, a key gene in the OXPHOS pathway, was upregulated in PDAC tumours compared to normal tissues." (PMID 40596639, 2025). "This supports the hypothesis that COA6 facilitates enhanced ATP synthesis through activation of the OXPHOS pathway, supplying the energy required for sustained tumour cell proliferation." (PMID 40596639, 2025). "Notably, AOC3, F8, and IL1A were found to be highly expressed in the normal group, while COA6, FKBP4, and LOXL2 were highly expressed in the tumours." (PMID 38577594, 2024). "The level of COA6 protein expression was also higher in LUAD tissues than normal lung tissues in the Clinical Proteomic Tumor Analysis Consortium (CPTAC) database (p < 0.05)." (PMID 36982777, 2023).
mitochondrial disease (4 papers, 2019 to 2024). "It is clear that Coa6 is essential for COX assembly, that it plays a role in the biogenesis of the CuA site, interacts with crucial factors in the IMS Cu delivery pathway, and that mutations to Coa6 are pathogenic and lead to mitochondrial disease." (PMID 31515291, 2019). "Abnormalities in COA6 may impair CcO assembly, resulting in decreased activity and causing multiple mitochondrial diseases." (PMID 39132153, 2024). "Patients with mutations in Coa6 suffer from mitochondrial disease due to complex IV deficiency." (PMID 31515291, 2019). "Current research on COA6 has mainly been concentrated on its role in mitochondrial metabolic diseases." (PMID 36982777, 2023).
cancer (3 papers, 2021 to 2024). A tumor composed of atypical neoplastic, often pleomorphic cells that invade other tissues. "These experiments demonstrated COA6 is pivotal in regulating cell proliferation, apoptosis, migration, and invasion, thereby promoting cancer progression in vitro." (PMID 39132153, 2024). "Nonetheless, our COA6 study has provided novel insights into the roles of COA6 in cancer progression." (PMID 36982777, 2023).
infection (1 paper, 2022). The state of being infected such as from the introduction of a foreign agent such as serum, vaccine, antigenic substance or organism. "The converse was observed in the COA3 and COA6 PDXs, in which STAT1 expression decreased with M002 infection." (PMID 35159029, 2022).
COA6 also shares sentences with these, for which no sentence is quoted: encephalomyopathies (1 paper); lactic acidosis (1); pancreatic ductal adenocarcinoma (1).